OR4E2 (olfactory receptor family 4 subfamily E member 2)
Description:
Olfactory receptor that is activated by the binding of organosulfur odorants with thioether groups such as (methylthio)methanethiol (MTMT) and bis(methylthiomethyl) disulfide (By similarity). Also binds odorants cis-cyclooctene and tert-butyl mercaptan (By similarity). The activity of this receptor is mediated by G proteins which activate adenylyl cyclase (By similarity).
Synonyms: OR14-42
Gene: Protein-coding gene on chromosome 14 (21,653,835 to 21,667,642, forward strand). Ensembl gene ENSG00000221977.
Subcellular location: Cell membrane
Pathways (Reactome):
Sensory Perception: Expression and translocation of olfactory receptors
Genetic constraint (gnomAD): Loss-of-function variants: 12 observed, 14.59 expected, observed/expected ratio (o/e) 0.82, 90% interval 0.53 to 1.33. The upper end of that interval is the gene's LOEUF score, 1.33, which puts it in group 5 of 6, group 1 being the genes least tolerant of losing a copy. Missense variants: 435 observed, 396.7 expected, observed/expected ratio (o/e) 1.1, 90% interval 1.01 to 1.19. Synonymous variants: 157 observed, 153.43 expected, observed/expected ratio (o/e) 1.02, 90% interval 0.9 to 1.17.
Homologues: Orthologues: chimpanzee OR4E2 (98% identical), macaque OR4E2 (97% identical), pig OR4E2 (87% identical), rabbit OR4E2 (87% identical), guinea pig OR4E2 (85% identical), rat Or4e2 (85% identical), mouse Or4e2 (85% identical), dog OR4E2 (82% identical). Paralogues in human: OR4E1 (62% identical), OR4S2 (55% identical), OR4K15 (53% identical), OR4C11 (52% identical), OR4K14 (52% identical), OR4K1 (51% identical), OR4X2 (51% identical), OR4Q3 (51% identical), OR4A15 (50% identical), OR4B1 (50% identical), OR4C5 (50% identical), OR4C3 (50% identical), and 116 more.
Diseases named in the same sentence as OR4E2 in open-access papers:
OR4E2 is named in the same sentence as 1 disease in open-access papers, as found by Europe PMC text mining. Sharing a sentence is not in itself a finding about the gene and the disease. The quoted sentences say what the papers report.
breast carcinoma (1 paper, 2023). "The chromosome 14 region where OR4E2 is located is co-amplified with human epidermal growth factor 2 (HER2), which is overexpressed in breast cancer." (PMID 38069004, 2023).